COSMOC (cell fate and sterol metabolism associated divergent transcript of MOCOS)
Gene: Long non-coding RNA gene on chromosome 18 (36,179,991 to 36,187,475, reverse strand). Ensembl gene ENSG00000260552.
Diseases named in the same sentence as COSMOC in open-access papers:
COSMOC is named in the same sentence as 1 disease in open-access papers, as found by Europe PMC text mining. Sharing a sentence is not in itself a finding about the gene and the disease. The quoted sentences say what the papers report.
Asperger syndrome (1 paper, 2021). "Surprisingly, COSMOC is strongly under-expressed in all ASD patients of our cohort with the exception of a patient affected by Asperger syndrome." (PMID 32327736, 2021).